RNU6-290P (RNA, U6 small nuclear 290, pseudogene)
Synonyms: LOC124901189
Gene: Small nuclear RNA gene on chromosome 5 (126,553,302 to 126,553,402, reverse strand). Ensembl gene ENSG00000202082.
Homologues: Orthologues: chimpanzee U6 (100% identical), mouse Gm25740 (85% identical), macaque U6 (79% identical), rat LOC120103229 (59% identical). Paralogues in human: RNU6-1316P (90% identical), RNU6-1145P (89% identical), RNU6-29P (88% identical), RNU6-38P (88% identical), RNU6-393P (88% identical), RNU6-20P (87% identical), RNU6-478P (87% identical), RNU6-639P (87% identical), RNU6-658P (87% identical), RNU6-16P (86% identical), RNU6-25P (86% identical), RNU6-28P (86% identical), and 1288 more.